TF (transferrin)
Diseases named in the same sentence as TF in open-access papers (continued):
Sharing a sentence is not in itself a finding about the gene and the disease.
anxiety disorder (1 paper, 2024). A category of psychiatric disorders which are characterized by anxious feelings or fear often accompanied by physical symptoms associated with anxiety. "We found that serum iron, ferritin and transferrin saturation were negatively correlated with the risk of anxiety disorders at genetically predicted level." (PMID 38547239, 2024). "IVW analysis revealed that increased serum iron, ferritin and transferrin saturation significantly associated with decreased risk of anxiety disorders." (PMID 38547239, 2024). "The causal associations of serum iron level, ferritin, transferrin saturation and TIBC with anxiety disorders were estimated, which may provide more evidence and proper suggestions to the intervention of anxiety disorders." (PMID 38547239, 2024). "Basing on IVW method, genetically predicted serum iron level, ferritin and transferrin had negative effects on anxiety disorders." (PMID 38547239, 2024).
babesiosis (1 paper, 2023). Babesiosis refers to a condition caused by microscopic parasites that infect the red blood cells. "Other identified proteins that differentiated uncomplicated from complicated babesiosis were various complement cascade components (CFI, CFP, C2, SERPING1, C8G), extracellular matrix components (TGFBI), acute phase proteins (ORM1, ITIH2, ITIH4, FGA, TF, RBP4) and lipoproteins (apoE)." (PMID 37353646, 2023).
bubonic plague (1 paper, 2022). A plague in which the bacteria have infected the lymphatic system. "Consequently, we speculated that the Ybt system acquiring iron from transferrin and lactoferrin plays a more important role than the other systems in the bubonic plague model." (PMID 35601093, 2022).
C. perfringens infection (1 paper, 2025). "Moreover, the findings underscore a coordinated effort of the host to mitigate the C. perfringens infection via activating immune (a.o., C3, CFH, MASP2, MBL2) and acute phase (CP, ORM, TF, ExFAB) related proteins." (PMID 40275387, 2025).
carcinoma in situ (1 paper, 2012). "In dermal carcinoma, as well as in carcinoma in situ, Arachis hypogaea, Artocarpus integrifolia, and Amaranthus leucocarpus lectins recognize the Galβ1-3GalNAc or TF antigen (Thomsen-Friedenreich antigen)." (PMID 23265237, 2012).
cardiac hypertrophy (1 paper, 2019). "Increase in expression of iron regulatory proteins TF, Tfrc, Fth-1, and Ftl-1 were also observed in heart tissues of rats which underwent constriction of the aorta and had cardiac hypertrophy." (PMID 31511561, 2019).
cerebral amyloid angiopathy (1 paper, 2018). "A number of mechanisms may be at play including decreased plasma iron due to abnormal transferrin desaturation and increased levels of oxidized hemoglobin and heme which abnormally bind and colocalize with amyloid-beta senile plaques causing cerebral amyloid angiopathy." (PMID 30356710, 2018).
Cerebral atrophy (1 paper, 2017). Atrophy (wasting, decrease in size of cells or tissue) affecting the cerebrum. "Cerebral atrophy was found to be regulated by two key players— Transferrin as well as ACHE." (PMID 28731430, 2017).
cerebral malaria (1 paper, 2024). A sequestration of Plasmodium falciparum in the brain, which can cause coma and/or seizures. "For instance, SLNs loaded with quinine dihydrochloride and conjugated with transferrin, aimed at treating cerebral malaria, demonstrated enhanced brain uptake compared to the free drug in solution, attributed to transferrin's facilitation of receptor-mediated transport." (PMID 39360065, 2024).
cerebral thrombosis (1 paper, 2008). "The data offered a potential therapeutic strategy in the regulation of TF expression in BMECs in vitro and suggest that PLA NPs may be an appropriate delivery vehicle for decoy strategy in the gene therapy of cerebral thrombosis." (PMID 19325834, 2008).
cervical squamous cell carcinoma (1 paper, 2025). A squamous cell carcinoma arising from the cervical epithelium. "TF expression was observed in 86.3% (145/163) of cervical squamous cell carcinoma and 85.2% (58/68) of adenocarcinoma but was absent in normal cervical tissues." (PMID 41009508, 2025).
cholangiocarcinoma (1 paper, 2021). A carcinoma that arises from the intrahepatic biliary tree (intrahepatic cholangiocarcinoma) or from the junction, or adjacent to the junction, of the right and left hepatic ducts (hilar cholangiocarcinoma). "Moreover, expressions of six TF genes (SP1, CREB1, MAX, FHL2, RFX1, and HIF1A) was positively correlated with the expression of ITGA6 and ITGB1 in cholangiocarcinoma tissues." (PMID 34199886, 2021).
Cholestatic liver disease (1 paper, 2020). "Since we know that bile acid retention in cholestatic liver diseases may disrupt cell and organelle membranes and that the synthesis of glycoprotein oligosaccharides takes place in the RER membrane, we made an attempt to test the glycosylation profile of serum transferrin in the course of PBC." (PMID 32911601, 2020).
Chronic diarrhea (1 paper, 2024). The presence of chronic diarrhea, which is usually taken to mean diarrhea that has persisted for over 4 weeks. "In monkeys with idiopathic chronic diarrhea, transferrin shows comparable or even better therapeutic effects than hydrocortisone." (PMID 38274126, 2024).
chronic myeloid leukemia (1 paper, 2025). "Imatinib mesylate, a clinically approved tyrosine kinase inhibitor (TKI) for chronic myeloid leukemia and gastrointestinal stromal tumors, is known to interact with transferrin and may be repurposed based on its newly predicted affinity for CHP1." (PMID 40723891, 2025).
chronic thromboembolic pulmonary hypertension (1 paper, 2021). Chronic thromboembolic pulmonary hypertension (CTEPH) is characterized by the persistence of thromboemboli in the form of organized tissue obstructing the pulmonary arteries. "Previous study showed that higher TF antigen, and TF mRNA in monocytes were displayed in chronic thromboembolic pulmonary hypertension (CTEPH) patients compared with control subjects." (PMID 34977488, 2021).
congenital disorder of glycosylation type I (1 paper, 2019). A congenital disorder of glycosylation involve disrupted synthesis of the lipid-linked oligosaccharide precursor. "Recent data suggested a reversible transferrin hypoglycosylation in untreated HFI patients mimicking congenital disorders of glycosylation type I consistent with an increase of asialo- and disialo-, and a decrease of tetrasialo-transferrin." (PMID 31591370, 2019).
coronary artery calcification (1 paper, 2025). Calcification of the coronary artery, used as a measure of coronary atherosclerosis, a risk factor for myocardial infarction. "In a cohort of 173 patients receiving maintenance hemodialysis, coronary artery calcification was quantified and related to iron parameters, including serum iron, transferrin saturation, and ferritin." (PMID 41155502, 2025). "Patients with severe calcification, defined as a coronary artery calcification score of 400 or higher, exhibited significantly lower serum iron and transferrin saturation." (PMID 41155502, 2025).
corticobasal syndrome (1 paper, 2025). Corticobasal syndrome (CBS) is a rare neurodegenerative disease characterized by multifaceted motor system dysfunctions and cognitive defects such as asymmetric rigidity, bradykinesia, limb apraxia, and visuospatial dysfunction. "Neither transferrin nor VCAM-1 has been studied in the context of progressive supranuclear palsy (PSP) or corticobasal syndrome (CBS)." (PMID 41225971, 2025).
cryptococcosis (1 paper, 2025). An acute or chronic, localized or disseminated infection by Cryptococcus neoformans. "They reported that the deletion of FRE4 reduced melanin production and that the mutant lacking FRE2 exhibited growth deficiency in medium containing heme or transferrin as the sole iron source and reduced virulence in a mouse model of cryptococcosis." (PMID 40443228, 2025).
cutis laxa (1 paper, 2021). Cutis laxa (CL) is an inherited or acquired connective tissue disorder characterized by wrinkled, redundant and sagging inelastic skin associated with skeletal and developmental anomalies and, in some cases, with severe systemic involvement. "Given the peculiar skin presentation, in order to investigate congenital disorders of glycosylation with cutis laxa, sialotransferrin IEF was performed, which showed normal transferrin distribution." (PMID 33275834, 2021).
delirium (1 paper, 2023). A disorder characterized by confusion; inattentiveness; disorientation; illusions; hallucinations; agitation; and in some instances autonomic nervous system overactivity. "Carbohydrate-deficient transferrin (CDT) and the γ-glutamyltransferase-CDT derived Anttila-Index are established biomarkers for sustained heavy alcohol consumption and their potential role to predict delirium and mortality in critically ill patients is not clear." (PMID 37854697, 2023).
diarrhoea (1 paper, 2005). "The gene(s) encoding the ETEC F4ab/ac receptors, involved in neonatal diarrhoea in pigs (a disease not yet described in humans), is located close to the TF locus on Sscr13." (PMID 16176575, 2005).
dilated cardiomyopathy (1 paper, 2010). Cardiomyopathy which is characterized by dilation and contractile dysfunction of the left and right ventricles. "We report an 11 year old Saudi boy with severe psychomotor retardation, seizures, strabismus, inverted nipples, dilated cardiomyopathy, and a type 1 pattern of serum transferrin isoelectrofocusing." (PMID 20398363, 2010).
disseminated candidiasis (1 paper, 2011). Systemic candidiasis occurs when Candida yeast enters the bloodstream and may spread (becoming disseminated candidiasis) to other organs, including the central nervous system, kidneys, liver, bones, muscles, joints, spleen, or eyes. "In vitro phenotypes of C. albicans Zn2-Cys6 TF mutants with hypo- or hyper-colonization phenotype in a mice model of disseminated candidiasis." (PMID 22073120, 2011).
Ectrodactyly-Ectodermal dysplasia-Cleft (EEC) syndrome (1 paper, 2025). "The TF p63 is a key regulator of keratinocyte differentiation during development, the disruption of which can lead to a spectrum of developmental disorders such as the Ectrodactyly-Ectodermal dysplasia-Cleft (EEC) syndrome." (PMID 40223810, 2025).
elephantiasis (1 paper, 2015). Enlargement of an area of the body due to obstruction within the lymphatic system and the resulting accumulation of lymph. "Also, transferrin is a recognized as a virulence determinant for Wuchereria bancroftti, the causal agent of elephantiasis, which is transmitted by the Aedes aegyptti in a circulative-propagative manner." (PMID 26091106, 2015).
endometrial stromal tumor (1 paper, 2017). Neoplasms of the endometrial stroma that sometimes involve the myometrium. "Intriguingly, among the TF genes with DM we also found JAZF1, a proto-oncogene affected by chromosomal translocations in endometrial stromal tumors." (PMID 28125717, 2017).
endometrioid adenocarcinoma (1 paper, 2009). An adenocarcinoma characterized by the presence of malignant glandular epithelial cells resembling endometrial cells. "Immunohistochemical analysis revealed a strong TF expression in mucinous and endometrioid adenocarcinomas, in addition to clear cell carcinomas." (PMID 19904262, 2009).
erythroleukemia (1 paper, 2014). Acute erythroid leukemia characterised by the presence of at least 50% erythroid precursors and at least 20% myeloblasts in the bone marrow. "Transferrin coated liposomes co-encapsulating Doxorubicin and Verapamil exhibited 5 and 3-fold cytotoxicity in Doxorubicin-resistant human erythroleukemia K562 cells compared to non-targeted liposomes and transferrin targeted liposomes with Doxorubicin alone respectively." (PMID 25071577, 2014).
essential thrombocytosis (1 paper, 2025). "A previous study revealed that tissue factor levels are elevated in patients with essential thrombocytosis and that the TF-dependent blood coagulation pathway is activated." (PMID 41210867, 2025).
extrahepatic cholestasis (1 paper, 2020). Impairment of the bile flow caused by an obstruction in the portion of the bile duct system located outside of the liver. "The profile of transferrin isoforms in PBC patients was compared with the transferrin profile in extrahepatic cholestasis." (PMID 32911601, 2020).
Fibroadenoma (1 paper, 2012). A benign tumor of the breast characterized by the presence of stromal and epithelial elements. "Our results suggest that expression of antigen TF and galectin-3 seems to participate in fibroadenoma development." (PMID 23265237, 2012).
galactosemia (1 paper, 2022). "The abnormal patterns found in GALE deficient patients are consistent with the serum transferrin glycosylation patterns in classic galactosemia." (PMID 36056436, 2022).
gas gangrene (1 paper, 2016). A severe condition resulting from bacteria invading healthy muscle from adjacent traumatized muscle or soft tissue. "Our studies on C. perfringens gas gangrene strain JIR325, a derivative of strain 13, showed that it is capable of utilizing both human hemoglobin and ferric chloride, but not human holo-transferrin, as an iron source for in vitro growth." (PMID 27637108, 2016).
gastric adenocarcinoma (1 paper, 2015). "The aim of this study was to investigate the inhibitory effect of Cerium in presence of transferrin on gastric adenocarcinoma cells in vitro." (PMID 26664465, 2015). "The purpose of this study was to evaluate the anti-tumor effect Cerium (lanthanides) on the growth and survival of gastric adenocarcinoma cells isolated from patients in the presence of transferrin in vitro." (PMID 26664465, 2015).
giardiasis (1 paper, 2023). An infection of the small intestine caused by the flagellated protozoan giardia lamblia. "Giardiasis showed higher reduction in the biochemical markers including ferritin, lactoferrin, iron, and transferrin among Gp 2, compared to Gp 1 and thus affected the swimmers’ scores." (PMID 36944683, 2023).
glutathione metabolism disorder (1 paper, 2025). "For example, the loss of TFRC in skeletal muscle SCs may contribute the absorption of non-transferrin-bound iron and cause Fe2+ accumulation, glutathione metabolism disorder, and lipid peroxidation, inducing skeletal muscle ferroptosis." (PMID 40938883, 2025).
Granuloma (1 paper, 2017). A compact, organized collection of mature mononuclear phagocytes, which may be but is not necessarily accompanied by accessory features such as necrosis. "In contrast, the necrotic center of a caseous granuloma showed accumulation of transferrin (TF), haptoglobin (HP), and hemopexin (HPX), which are potent extracellular sequesterers of Fe3+, Hb, and heme, respectively." (PMID 28811344, 2017).
gynecological cancer (1 paper, 2018). "Various factors including hemoglobin, total protein, albumin, and transferrin are used to evaluate the nutritional status in patients with gynecological cancer." (PMID 29193777, 2018).
hearing loss (1 paper, 2022). "Of 1280 probands whose genomic DNA was subjected to molecular genetic testing, TF genes were responsible for hearing loss in 2.6%." (PMID 36140227, 2022). "The results of this study reveal the genetic load of TF gene alterations among a cohort with non-syndromic hearing loss." (PMID 36140227, 2022). "However, only a handful of TF variants are known to cause hearing impairment, and their clinical phenotypes and genotypes in the context of hearing loss remain poorly understood." (PMID 36140227, 2022).
Helicobacter infection (1 paper, 2012). "Chronic Helicobacter infection of INS- GAS mice resulted in decreased serum iron, transferrin saturation and hypoferritinemia and increased Total iron binding capacity (TIBC)." (PMID 23185574, 2012).
Huntington disease (1 paper, 2022). Huntington disease (HD) is a rare neurodegenerative disorder of the central nervous system characterized by unwanted choreatic movements, behavioral and psychiatric disturbances and dementia. "Both CLU and TF are involved in oxidative stress response, apoptosis, and DNA damage response (DDR) and have been reported to be involved in Huntington’s disease pathogenesis." (PMID 36009409, 2022).
hydatidosis (1 paper, 2020). "Related studies have reported that NFKB1 is the core TF regulating hydatidosis, and it may participate in the inflammatory process of hydatidosis." (PMID 32596042, 2020).
hypospadias (1 paper, 2023). Hypospadias is the displacement of the urethral meatus on the ventrum of the penis. "Several of these MeSH terms are associated with TF (transferrin), EGF (epidermal growth factor), MMP14 (Matrix metallopeptidase 14), CDH1 (Cadherin 1), and F13A1 (Coagulation factor XIII A chain) genes, related to CLJ and hypospadias." (PMID 37238140, 2023).
immune thrombocytopenia (1 paper, 2024). "Genetic defects in TF sialylation are frequent in pediatric immune thrombocytopenia (ITP) and are often associated with high titers of anti-TF antibodies and increased response to IFNs." (PMID 38777879, 2024).
Impotence (1 paper, 2023). Inability to develop or maintain an erection of the penis. "On the other hand, the least preferred answer options were Conduct research into impotence and hormonal problems (8.8%), Implement transferrin saturation tests in initial and maintenance phase (8.4%) and Research the epidemiological aspects of HC (6.4%)." (PMID 37503783, 2023).
infantile spasms (1 paper, 2022). A rare epilepsy syndrome characterized by onset of epileptic spasms in infants between 2 and 12 months of age, and rarely up to 24 months. "Later, in 2016, Western blot analysis of a 6-year-old female patient who developed infantile spasms showed the normal glycosylated transferrin isoforms." (PMID 35327592, 2022).
intrauterine growth restriction (1 paper, 2012). "Upon placenta and fetal injury, the TF gene is upregulated in women with recurrent miscarriages and intrauterine growth restriction." (PMID 23119001, 2012).
invasive breast carcinoma (1 paper, 2013). A carcinoma that infiltrates the breast parenchyma. "Compared to the endothelial cells HCAEC, high levels of TF mRNA were detected in the basal-like, invasive breast cancer cell lines Sum102, MDA-MB-231, and Sum149, and also in the non-cancerous breast epithelial cells ME16C2." (PMID 23320987, 2013).
ischemia reperfusion injury (1 paper, 2019). Adverse functional, metabolic, or structural changes in ischemic tissues resulting from the restoration of blood flow to the tissue (reperfusion), including swelling; hemorrhage; necrosis; and damage from free radicals. "In conclusion, a novel carrier targeting the BBB was developed using enkephalin-loaded exosomes containing transferrin, called enkephalin-tar-exo, resulting in protecting brain from ischemia-reperfusion injury, providing a novel approach to reduce brain injury." (PMID 30949500, 2019).
Kaposi's sarcoma (1 paper, 2025). A malignant neoplasm characterized by a vascular proliferation which usually contains blunt endothelial cells. "KSHV showed high co-occurrence with ‘Genetic_Function’ and ‘Neoplastic_Process’, with the highest TF–IDF values for ‘DNA Replication’ and ‘Kaposi Sarcoma’." (PMID 40996719, 2025).
keratitis (1 paper, 2025). A corneal disease that is characterized by inflammation of the cornea. "Clinical studies reported various corneal changes, including keratitis, epithelial thinning, and microcyst formation, in patients treated with ADCs such as belantamab mafodotin (anti-BCMA), tisotumab vedotin (anti-TF), and Elahere (anti-FRα)." (PMID 41155607, 2025).
kidney cancer (1 paper, 2015). Primary or metastatic malignant neoplasm involving the kidney. "Other TF networks we identified, such as RUNX1/2 and its association with poor outcome in kidney cancer, have never been reported and will form the basis for future studies." (PMID 25994056, 2015).